CD4 (CD4 molecule)
Diseases named in the same sentence as CD4 in open-access papers (continued):
Sharing a sentence is not in itself a finding about the gene and the disease.
infection (continued). "Here we assessed the T helper cell phenotypes in threadworm-infected patients and experimental murine infections with focus on CD4+ T cells co-expressing markers of Th2 and Th1 differentiation." (PMID 28676845, 2017). "This antigen-specific subset is known to be induced by antigen exposure, such as during infection or immunization, from naïve CD4 T cells in the periphery, and to subsequently suppress Th1 responses." (PMID 28871201, 2017). "Before infection, WT and Cyld−/− mice harbored equal numbers of CD4+ T cells in the blood and brain." (PMID 28203236, 2017). "This infection of Langerhans cells and interstitial dermal dendritic cells results in an impaired ability to stimulate CD4+ helper T cell responses." (PMID 28768873, 2017). "Conversely, the stage 1 infected cells, which presumably represent cells at the time of or shortly after infection, exhibited significantly higher surface CD4 and CD3 relative to uninfected (and tat/rev+) cells in some specimens." (PMID 28654687, 2017). "The most abundant population of CD4+ T cells was CD44high Ly6C-/low CD127-/low (“effector T cells”), consistent with the accumulation of effector CD4+ T cell in BM during infection with L. donovani." (PMID 28671989, 2017). "Changes during asymptomatic malaria infection and following parasite clearance suggest short- and long-term effects of infection on γδ T cells and CD4+ T cells, as well as involvement of immunoregulation." (PMID 28821806, 2017). "After six weeks of infection, a significant portion of the CD4 T cells (1 to 2%) recognized Ag85B regardless if the animals were infected with one or the other strain." (PMID 28436493, 2017). "During blood stage propagation of Plasmodium infection, CD4+ T cells and humoral immune responses are essential components to control infection." (PMID 28293237, 2017). "Langerhans cells have also emerged as key players in the activation of CD4+ T follicular helper cells (Tfh), which are required for germinal center formation and antibody affinity maturation in response to infection or vaccination." (PMID 29379502, 2017). "During the course of infection with L. major, BALB/c (a susceptible strain) CD4+ cells and neutrophils produced more IL-17 than did cells from (resistant) C57BL/6 mice." (PMID 29163510, 2017). "The TDB-containing liposomal adjuvant CAF01 has been used in several experimental infection models, induces long-lived protective CD4 memory T cells in mice, and also appears to be effective in humans." (PMID 29312343, 2017). "By analyzing the immunity that develops following primary infection, it has been shown that protection against reinfection is multifactorial, with CD4+ T cells and antibody playing predominant roles (9, 11, –, 13)." (PMID 28739831, 2017). "Whereas blood CD4+ T cell infection was partially decreased by TFV starting at 1 μM, the same 1 μM dose of TFV had no anti-HIV effect on endometrial CD4+ T cells." (PMID 29255206, 2017). "Models of SIV transmission in the female genital tract show that infection begins with the establishment of a productive focus of infected CD4 T-cells that expands through local viral replication, followed by systemic dissemination after several days." (PMID 28893286, 2017). "Surprisingly, except for one animal CD4+ T cell recipient mice recovered until day 20 and survived the infection." (PMID 28222146, 2017). "Infection with a CCR5-tropic SIV, including the SIVmne027 backbone used in this study, leads to significant loss of CD4+ TEM cells in mucosal tissues, such as the gut." (PMID 28542550, 2017). "Epicutaneous infection models with the pathogens C. albicans or S. aureus have demonstrated clear roles for LC in priming protective CD4+ T cell responses, and ionizing radiation specifically activates LC to prime Treg in LN." (PMID 29379502, 2017). "During the blood-stage of infection, CD4+ T cells play a critical role in balancing the immune response." (PMID 29085373, 2017).
infection (continued). "CD4+ T-cells are the central mediators of immune response in humans, crucially coordinating cellular and humoral immune responses against infections." (PMID 28588579, 2017). "At six weeks post-infection CD4 and CD8 memory T cells had accumulated in the lung tissues, but it is not known which epitopes these cells are targeting." (PMID 28475122, 2017). "The frequency of CD11a+ CD49d+ CD4+ T cells has been used to measure polyclonal antigen specific CD4+ T cell responses in a variety of infections including RSV." (PMID 28953978, 2017). "Although both groups succumbed to challenge, CD4-depleted animals showed fewer differentially expressed genes (DEGs) 4 days post infection (dpi) and succumbed to infection 2 days later compared to negative control animals." (PMID 28428619, 2017). "A high-lung viral titer at day 7 after challenge was observed in the M2e5x VLP CD4KO group, which is similar to the one observed in naïve infection, suggesting a role of CD4 T cells in M2e-immune mediated cross-protection." (PMID 29276514, 2017). "CD4+ T-cell-mediated antigen presentation also occurs in vivo in the course of infection, and induces the generation of central memory CD8+ T cells with low PD-1 expression." (PMID 29147022, 2017). "The multiple levels at which Vpu acts to prevent export of CD4 from the ER underscore the importance of ensuring complete depletion of CD4 from the plasma membrane for progression of the infection." (PMID 29088112, 2017). "Research has also found that all forms of HIV DNA persist in resting CD4 cells, suggesting that there is replenishment of the reservoir, either by reactivation or by infection." (PMID 29088095, 2017). "We did not observe any differences in the frequencies of Foxp3+ Tregs among CD4+ T cells during long-term depletion of DC in P. yoelii-infected mice, whereas starting depletion at day 4 of infection resulted in decreased percentages of Tregs." (PMID 29085373, 2017). "We analyzed the relationship between NKG2A and NKG2C receptor expression on the surface of NK cells from PHI subjects and CD4+ T cell counts, or viral loads, at the time of 360-day infection." (PMID 28979268, 2017). "Human immunodeficiency virus has tropism for CD4+ T cells, which are progressively depleted during primary infection." (PMID 29085360, 2017). "In contrast, CD4low.c24-rev recovered infectivity, exhibiting similar levels of infection to the controls on high CD4 cells, and also developed the highest infectivity of the panel on cells with low CD4." (PMID 28264054, 2017). "The median baseline CD4+ T-cell count was 612 cells/mm3 in patients with genotype 1 infection, and 731 cells/mm3 in patients with genotype 4 infection." (PMID 28948180, 2017). "Interrupting IL-4Rα expression prior to the secondary infection resulted in reduced proportions and total numbers of CD4+CD44+ T cells expressing Gata-3 compared to control mice given vegetable oil." (PMID 28651009, 2017). "Additional studies specifically tracking CD4 CTL activity to various infections or vaccines in young and elderly adults will provide further insight into this observation." (PMID 28167943, 2017). "Access to this compartment also increases viral contact with resident dendritic cells (DCs), which although inefficiently infected, can capture virions and transfer them to CD4+ T cells by trans-infection." (PMID 28207890, 2017). "Both Th1 (IFN-γ) and/or Th17 (IL-17) cells have been associated in the pathogenesis of EAU12, hence we investigated the cytokine profile of the HEL-specific CD4+ T cells activated in our infection model." (PMID 29079770, 2017). "IL10 production by IFNγ+ CD4 T cells was higher in younger children and in those with high-parasite burden during recent infection." (PMID 29097996, 2017). "CCR5 mediated entry into CD4 T cells was specific since the CCR5 antagonist maraviroc was able to block infection." (PMID 28253319, 2017).
infection (continued). "This indicated that during infection with S. Typhimurium the CD4+CD25+ T cell subset was specifically being killed in an apoptosis-dependent fashion." (PMID 28584281, 2017). "On day 5 post infection, similar frequencies of CD4+ cells were observed in the skin explants from WTCD4cre and KOCD4cre mice, both significantly enhanced relative to mock-treated controls." (PMID 28824171, 2017). "Two weeks post infection, the frequency of CD4+IFNγ+ and CD4+IL-4+ dLN T cells represented in average 0.6 and 0.13% of total CD4+ T cells, respectively." (PMID 29067025, 2017). "Even in animals vaccinated prior to M.tb DK9897 infection, there was barely a detectable CD4 T cell response specific for EsxA in the lung." (PMID 28436493, 2017). "Under these conditions, the majority of antigen-specific CD4+ T cells proliferated extensively in the spleen and lymph nodes within 4 days of infection and produced IFN-γ." (PMID 29079770, 2017). "R. typhi-infected C57BL/6 RAG1−/− that succumbed to the infection despite CD4+ T cell transfer still showed enhanced activation of MΦ and microglia in the CNS despite bacterial elimination." (PMID 28770333, 2017). "Most importantly, the high concentration of HIV in the lymphoid follicle promotes infection of CD4+ T cells, which is critical for the pathogenesis of the virus." (PMID 28197139, 2017). "A secondary siRNA screen of the identified signaling factors revealed several new mediators of HIV‐1 trans‐infection of CD4+ T cells in DCs, including the dynein motor protein Snapin." (PMID 28923824, 2017). "Such a property is a significant advantage for infection of primary macrophages and CD4+ T cells that express low levels of CD4." (PMID 28752105, 2017). "Studies on H. polygyrus and T. gondii co-infection in mice have so far focused on a previous infection with helminths and have shown that initially CD4+ and CD8+ T cell immunity against T. gondii is suppressed in mice." (PMID 28791259, 2017). "The mechanism by which l-citrulline metabolism affects CD4+ T cell accumulation and/or growth during infection remains to be further examined with detailed longitudinal studies." (PMID 29201027, 2017). "In other studies, Ag85B-specific CD4+ effector memory T cells (TEM) were shown to control infection in the lungs, and CD8+ T cells also protect against Mtb, particularly during LTBI." (PMID 29312295, 2017). "Here, we observe that PFI-1 and (+)-JQ1 enhance HIV infection, likely by promoting LTR transcription and thereby disfavoring immediate viral silencing following infection of unstimulated primary CD4+ T cells." (PMID 28114951, 2017). "Given the rarity of this infection in our cohort, we suspect that prophylaxis is routinely being used in those with CD4 count <50 cells/mm3; however, mortality rates continue to be high in those in whom disseminated NTM infections develop." (PMID 28221103, 2017). "Inhibitory NK receptors CD94/NKG2A have been shown to be upregulated on a subset of activated CD8+ T cells and possibly CD4+ T cells in response to infection." (PMID 28475642, 2017). "It was previously reported that mice depleted of CD4 T cells fail to clear the virus, implicating CD4 T cells in control of LCMV clone 13 the infection." (PMID 28993768, 2017). "Participants with sequences had a shorter duration of infection, lower CD4 counts, higher viral loads, and were less likely to be treatment experienced (p<0.0001 for all)." (PMID 28961263, 2017). "Significantly increased levels of IFNγ-producing CD4+ cells were found in skin surrounding early secondary lesions compared to uninfected and primary infection sites." (PMID 28724920, 2017). "With one exception, vaccinated animals maintained CD4 + T cells in the blood early after infection, but following the first 100 days a slow decline was observed." (PMID 28302457, 2017). "The adoptive transfer of purified WT CD4+ T cells protects Il18r1−/− and Myd88−/− mice against infection with T. cruzi." (PMID 28895840, 2017).
infection (continued). "We looked therefore for the presence of IL-9+ILC2 and Th9 cells in infection by characterizing IL-9-producing Lin− and CD4+ T cells in the lung." (PMID 28090087, 2017). "Given our previous findings of a decrease in HA-specific CD4 T cells and HA-specific antibody following secondary heterosubtypic challenge, we first sought to determine the effect of secondary infection on the availability of viral antigen." (PMID 28493882, 2017). "Depletion of either CD4+ or CD8+ T cells during P. berghei ANKA luc infection prevented the development of ECM in anti-IL-10R antibody-treated mice." (PMID 28396319, 2017). "Studies conducted with viral pathogens, such as HCV, HBV, and LCMV, have reported that CD4 T cell dysfunction observed during the chronic phase of the infection affects CD8 T cell functionality." (PMID 29163509, 2017). "We next investigated the role of proteins in the HIV‐1 DC signalosome in HIV‐1 trans‐infection to CD4+ T cells by conducting a secondary siRNA screen." (PMID 28923824, 2017). "Vaccine of calnexin in glucan particles elicited calnexin-specific CD4+ T cells and resistance to infection by B. dermatitidis, H. capsulatum, Pseudogymnoascus (Geomyces) destructans, Fonsecaea pedrosoi, and A. fumigatus." (PMID 28344577, 2017). "Whole genital tracts and spleens were harvested from wild-type C57BL/6 mice and C57BL/6 mice treated with anti-CD4 and anti-Ly6G at days 7 (early) and 21 (late) after secondary infection." (PMID 28739831, 2017). "The level of p24 from CD4+ T cells transduced with SaCas9/sgRNA #8 or #9 was markedly decreased compared with that of cells transduced with empty vector at 3–5 days post-infection." (PMID 29141633, 2017). "In CD4+ T-cells isolated from blood, a decrease in the frequency of IL-10 positive T-cells was observed at 48 and 72h post-infection." (PMID 28880895, 2017). "Recent studies have demonstrated that the balance between Th17-mediated protection and pathology is crucial for defining the outcome of infections at the mucosa with IL-17 attracting IFN-γ-producing CD4+ Th1 cells to the lungs to control the infection." (PMID 29259310, 2017). "R. typhi was not detectable anymore even in those mice that succumbed to the infection despite CD4+ T cell transfer." (PMID 28770333, 2017). "While ULBP-1, ULBP-2/5/6, and ULBP-3 are rarely expressed on healthy primary CD4+ T cells, it is well established that infection with several laboratory strains of HIV can induce their surface expression." (PMID 29023371, 2017). "In concordance with temporary disease, GPT levels significantly increased in CD4+ T cell recipients until day 14 post infection, reaching comparable levels as in infected control mice." (PMID 28222146, 2017). "We found that, when co-stained with HIV+ RNA, the CTLs are juxtaposed to the infected CD4+ T cells in B cell follicles, indicating the ability of these follicle-infiltrating CTLs to control the infection of TFH cells." (PMID 28620380, 2017). "In contrast, the expansion of CD4+CD25+Foxp3+ regulatory T cells (Tregs) and excessive release of proinflammatory cytokines during infection enhance host susceptibility to infection." (PMID 28769924, 2017). "At the time of infection, CD4 cell count remained low (0.16 and 0.17 × 109/l) and total Ig had declined by to 4.8 and 7.5 g/l, respectively." (PMID 27688979, 2016). "A statistically significant 2-fold increase in CD11c− cDC, CD14+ monocytes, and 3-fold increase in the frequency of and CD4+MHC class II− pDC was observed after infection." (PMID 27008425, 2016). "In order to confirm that the defect in virus replication in UNG2- and RPA32-depleted cells was related to a defect in the reverse transcription (RT) process, total viral DNA reverse transcripts were quantified 7 h after infection of HeLa-CD4 cells." (PMID 27068393, 2016). "A subset of subset of CD4 T cells called follicular helper T (TFH) cells play a critical role in facilitating an effective B cell response during infection." (PMID 26965109, 2016).
infection (continued). "This is motivated by the clinical interest in investigating the factors that determine the characteristics of long-term response to HAART, in particular the influences of baseline CD4 count and the time elapsed from infection to treatment initiation." (PMID 27633882, 2016). "These activated (effector or memory) CD4 T cells then recirculate through various tissues to aid infection clearance and protect against pathogen re-exposure." (PMID 27280403, 2016). "Efficient infection of CD4+ T-cells requires cell-cell contacts and coordinated steps of the virus infectious cycle with events in the cell-cell adhesion process." (PMID 27776189, 2016). "As the dual-tropic R3A can also utilize CXCR4 for infection, we found R3A replication in CD4 T cells wasn’t significantly affected by TAK-779 treatment, as measured by intracellular p24 staining or extracellular HIV-1 RT levels." (PMID 27026376, 2016). "Exacerbation of infection was attributable to enhanced production of IL-4 by CD4+ T cells and more Th2 in the lungs." (PMID 27302755, 2016). "To investigate how CCR5 interaction during dual-tropic R3A infection contributes to CD4 T cell depletion, we treated R3A infected cells with the CCR5 antagonist TAK-779." (PMID 27026376, 2016). "CD4+ T cells were isolated via MACS from spleen or lung cell suspensions derived from Mtb H37Ra-infected WT mice at 4 weeks post-infection were co-cultured with Rv2882c-treated BMDMs derived from uninfected mice for 3 days." (PMID 27711141, 2016). "Comparisons between the tumor immunotherapy and infection models reveal that different stimuli can induce distinct transcription factor expression in CD4 CTL with dual costimulation inducing Eomes and IAV infection inducing T-bet and Blimp-1." (PMID 27014272, 2016). "Both the absolute numbers of CD38+ in CD4+ T cells and relative frequency of CD38+ versus CD38- CD4+ T cell were increased upon infection." (PMID 27662621, 2016). "Conversely, infection of PBMC with ΔlspA reduced HIV infectivity of CD4+ T cells by 40% relative to BCG-infected cells (p<0.05)." (PMID 26807859, 2016). "We have recently shown that the frequency of circulating CD38+ CD4+ T cells was significantly increased following experimental infection with P. falciparum and inversely correlated with parasite levels." (PMID 27930660, 2016). "Following infection there were similar numbers of LLO-specific CD4 T cells on day 7 and 14 post infection in both groups of mice." (PMID 27588422, 2016). "Splenic IL-10+ CD4+ T cell frequencies also contracted rapidly, remaining at low but significant levels during the remaining course of infection." (PMID 27926930, 2016). "This assessed the levels of infection in CD4+ T cell subsets and monocyte-macrophages during persistent infection." (PMID 26996968, 2016). "Postnatal infection lead to increased CD4+FoxP3+T-cells frequencies in adult descendants, mostly in SIM mice - Inunstimulated cultures, the infected groups showed a higher frequency ofCD4+FoxP3+ T-cells compared with the uninfected control group." (PMID 26872339, 2016). "In contrast, anti–IL-10R administration led to a significant increase in Ag-experienced splenic CD4+ T cell numbers during secondary infection." (PMID 27630165, 2016). "Despite the effects on the innate immune response during primary infection, anti–IL-10R administration caused a slight decrease (rather than the expected increase) in the numbers of Ag-experienced CD4+ T cells during the early phases of primary infection." (PMID 27630165, 2016). "Accordingly, in P. yoelii 17XNL infection we observed a profound thymic atrophy with a reduction in the percentage of double positive cells (CD4+CD8+) and an increase in the percentage of single positive (CD4+ and CD8+) and double negative cells (CD4-CD8-)." (PMID 27446022, 2016).